TBC1D5 (TBC1 domain family member 5)
Description:
May act as a GTPase-activating protein (GAP) for Rab family protein(s). May act as a GAP for RAB7A. Can displace RAB7A and retromer CSC subcomplex from the endosomal membrane to the cytosol; at least retromer displacement seems to require its catalytic activity. Required for retrograde transport of cargo proteins from endosomes to the trans-Golgi network (TGN); the function seems to require its catalytic activity. Involved in regulation of autophagy. May act as a molecular switch between endosomal and autophagosomal transport and is involved in reprogramming vesicle trafficking upon autophagy induction. Involved in the trafficking of ATG9A upon activation of autophagy. May regulate the recruitment of ATG9A-AP2-containing vesicles to autophagic membranes.
Synonyms: KIAA0210
Tractability: Antibody: UniProt places it where antibodies can reach, with high confidence. PROTAC: ubiquitination databases record sites on it; its protein half-life has been measured.
Gene: Protein-coding gene on chromosome 3 (17,157,162 to 18,444,817, reverse strand). Ensembl gene ENSG00000131374.
Subcellular location: Endosome membrane; Cytoplasmic vesicle, autophagosome
Subcellular location (Human Protein Atlas): Vesicles; Golgi apparatus
Gene Ontology:
Molecular function: AP-2 adaptor complex binding; protein binding; protein-containing complex binding; retromer complex binding; GTPase activator activity
Biological process: autophagy; macroautophagy; positive regulation of receptor internalization; regulation of cilium assembly; response to starvation; retrograde transport, endosome to Golgi
Cellular component: AP-2 adaptor complex; Atg1/ULK1 kinase complex; autophagosome; endosome membrane; retromer complex; Golgi apparatus; cytoplasm; cytosol
Genetic constraint (gnomAD): Loss-of-function variants: 53 observed, 76.61 expected, observed/expected ratio (o/e) 0.69, 90% interval 0.55 to 0.87. The upper end of that interval is the gene's LOEUF score, 0.87, which puts it in group 3 of 6, group 1 being the genes least tolerant of losing a copy. Missense variants: 801 observed, 870.24 expected, observed/expected ratio (o/e) 0.92, 90% interval 0.87 to 0.98. Synonymous variants: 300 observed, 311.96 expected, observed/expected ratio (o/e) 0.96, 90% interval 0.87 to 1.06.
Homologues: Orthologues: chimpanzee TBC1D5 (99% identical), macaque TBC1D5 (98% identical), rabbit TBC1D5 (93% identical), dog TBC1D5 (90% identical), mouse Tbc1d5 (90% identical), rat Tbc1d5 (88% identical), pig TBC1D5 (85% identical), guinea pig TBC1D5 (85% identical), tropical clawed frog tbc1d5 (69% identical), zebrafish tbc1d5 (65% identical). Paralogues in human: TBC1D17 (13% identical), TBC1D15 (13% identical), TBC1D9B (12% identical), TBC1D9 (12% identical), EVI5L (11% identical), EVI5 (11% identical), RABGAP1L (11% identical), TBC1D8B (11% identical), RABGAP1 (10% identical), TBC1D10B (10% identical), USP6NL (10% identical), TBC1D16 (10% identical), and 33 more.
Diseases named in the same sentence as TBC1D5 in open-access papers:
TBC1D5 is named in the same sentence as 15 diseases in open-access papers, as found by Europe PMC text mining. Sharing a sentence is not in itself a finding about the gene and the disease. The quoted sentences say what the papers report.
Alzheimer disease (2 papers, 2018 to 2023). A progressive, neurodegenerative disease characterized by loss of function and death of nerve cells in several areas of the brain leading to loss of cognitive function such as memory and language. "Alcohol downregulates TBC1D5, which contributes to alcoholic liver disease as well as to Parkinson’s disease and Alzheimer’s disease." (PMID 37217680, 2023). "Although somewhat speculative, it is tempting to suggest that the interaction between the retromer CSC and TBC1D5 could therefore be an attractive target for therapeutic intervention in neurodegenerative diseases such as Parkinson's disease and Alzheimer's disease." (PMID 29777037, 2018).
fatty liver disease (1 paper, 2022). A reversible condition wherein large vacuoles of triglyceride fat accumulate in liver cells via the process of steatosis. "TBC1D5 encodes a GTPase-activating protein involved in hepatic lipophagy, which protects the liver from alcohol-induced fatty liver disease." (PMID 36581877, 2022).
oral squamous cell carcinoma (1 paper, 2023). "For example, tumor‐resident F. nucleatum triggers the GalNAc/autophagy/TBC1D5 signaling in oral squamous cell carcinoma (OSCC), driving tumor‐associated macrophage (TAM) formation, and OSCC progression." (PMID 38868430, 2023).
renal cell carcinoma (1 paper, 2024). "GSEA analysis using the TCGA-KIRC database indicated that TBC1D5 was highly involved in tumor metastasis, cancer, and renal cell carcinoma-related pathways in ccRCC." (PMID 38419050, 2024).
renal clear cell carcinoma (1 paper, 2024). "The regulatory mechanism of TBC1D5 in renal clear cell carcinoma (RCC) was investigated by shhif-2α, shTBC1D5, mimic, inhibitor, ChIP and Luciferase experiments." (PMID 38419050, 2024). "The expression of TBC1D5 in renal clear cell carcinoma was confirmed by database analysis, immunohistochemistry, PCR and Western blot." (PMID 38419050, 2024).
tumor (4 papers, 2020 to 2025). "In 24 clinical specimens pathologically diagnosed as ccRCC and their corresponding normal adjacent tissue, TBC1D5’s mRNA level was lower in tumor samples." (PMID 38419050, 2024). "The results show that TBC1D5 is crucial in regulating ccRCC lipid metabolism and tumor progression mediated by HIF-2α." (PMID 38419050, 2024). "As the potential critical gene that links the HIF-2α and TBC1D5 pathway, functional rescue experiments were conducted to illustrate further the impact of TBC1D5 in the HIF-2α mediated tumor progression and lipid accumulation in ccRCC." (PMID 38419050, 2024). "Chloroquine and rapamycin were used to verified the key role of autophagy in effects of TBC1D5 on tumor cell." (PMID 38419050, 2024). "TBC1D5 suppresses the progression and lipid accumulation of ccRCC by regulating the level of autophagy in tumor cells." (PMID 38419050, 2024). "Specifically, TBC1D5 is significantly underexpressed in ccRCC, serving as a tumor suppressor which inhibits tumor progression and lipid accumulation, and is negatively regulated by HIF-2α." (PMID 38419050, 2024). "TBC1D5 expression was lower in tumor specimens with more advanced T stage (T3 or T4), M stage (M1), tumor stage, and histological grade." (PMID 38419050, 2024). "Overall, TBC1D5 suppressed the proliferation, migration, invasion, and lipid droplet accumulation of ccRCC, suggesting TBC1D5 is a potential tumor suppressor." (PMID 38419050, 2024). "TBC1D5 overexpression in ccRCC can suppress tumor cells’ proliferation, migration, and invasion abilities." (PMID 38419050, 2024). "Mechanism studies have shown that HIF-2α regulates TBC1D5 through hsa-miR-7-5p in ccRCC, thereby affecting tumor progression and lipid metabolism through autophagy." (PMID 38419050, 2024). "Upregulated genes were primarily associated with cell adhesion/invasion/metastasis (ELMO2, ADAM9, DLG1, TRPM7), metabolism/mitochondrial function (FAM120A, DARS2), and cellular transport/axonal trafficking (KIF1B, TBC1D5), indicating the presence of tumor microenvironment stress." (PMID 41404060, 2025). "Notably, our rescue experiments demonstrated that TBC1D5 is vital in the tumor-promoting effects of HIF-2α since TBC1D5 knockdown reversed decreased proliferation, migration, invasion, and lipid accumulation caused by HIF-2α knockdown." (PMID 38419050, 2024). "Through these experiments, we proved that TBC1D5 is a gene regulated by HIF-2α in ccRCC, inhibiting HIF-2α promoted proliferation, migration, and invasion ability of tumor cells and is vital in suppressing cancer." (PMID 38419050, 2024). "We observed a higher mRNA expression of TBC1D10C, TBC1D4, TBC1D12, TBCK, TBC1D5, TBC1D30 and a lower expression of TBC1D24 in patients with tumor compared with tumor free patients." (PMID 33194704, 2020).
infection (2 papers, 2017 to 2020). The state of being infected such as from the introduction of a foreign agent such as serum, vaccine, antigenic substance or organism. "TBC1D5 knockdown caused a marked inhibition of infection comparable with the effect of expressing JX2." (PMID 32521275, 2020). "We next performed co-immunoprecipitation experiments to assess assembly of the retromer-TBC1D5 complex in response to infection." (PMID 32521275, 2020). "Infection with wild-type HPV PsV but not the HPV DM mutant caused the VPS35-positive puncta to largely co-localize with the TBC1D5-positive puncta (center and bottom rows, and S6F)." (PMID 32521275, 2020). "Finally, we tested whether TBC1D5 plays a functional role during infection with L. pneumophila." (PMID 29146912, 2017). "Although the JX2-TBC1D5 interaction was observed in extracts of uninfected cells far more TBC1D5 was co-immunoprecipitated from extracts of infected cells (compare lane 4 with lane 3), even though infection did not increase the total amount of TBC1D5." (PMID 32521275, 2020). "Similarly, PLA showed enhanced association between JX2 and TBC1D5 in infected cells, and immunofluorescence showed that infection with wild-type but not DM mutant HPV16 PsV caused dramatic co-localization of JX2 (but not FA) and TBC1D5." (PMID 32521275, 2020). "Infection with wild-type HPV16 PsV increased co-immunoprecipitation between TBC1D5 and VPS35 whereas infection with the DM mutant PsV did not (lanes 4–6)." (PMID 32521275, 2020).
heart (1 paper, 2021). "Our study sheds light on the important role of retrograde transport in the regulation of lysosomal function in ischemic conditions and suggests that TBC1D5 might be a possible therapeutic target for the ischemic heart." (PMID 35004909, 2021).
TBC1D5 also shares sentences with these, for which no sentence is quoted: cancer (3 papers); Parkinson disease (2); alcoholic liver diseases (1); autistic spectrum disorder (1); Legionnaires' disease (1); neurodegenerative disease (1); skin cutaneous melanoma (1).